XBP1 (X-box binding protein 1)
Diseases named in the same sentence as XBP1 in open-access papers (continued):
Sharing a sentence is not in itself a finding about the gene and the disease.
vitiligo (18 papers, 2009 to 2025). Generalized well circumscribed patches of leukoderma that are generally distributed over symmetric body locations and is due to autoimmune destruction of melanocytes. "This is particularly relevant to piebalding as XBP1 is linked to pigment loss as a candidate gene for vitiligo in humans, and loss of a predicted XBP1 binding site near EDNRB2 is associated with plumage depigmentation in ducks." (PMID 37862332, 2023). "In the present study, we aimed to investigate the association of X-box Binding Protein 1 (XBP1) and Interleukin-17A (IL-17A) polymorphisms and monitor their systemic as well as skin expression levels in vitiligo patients from Gujarat population in India." (PMID 35046957, 2021). "In conclusion, the present study identifies XBP1 rs2269577 polymorphism as genetic susceptibility loci for vitiligo in Gujarat population." (PMID 35046957, 2021). "Our results suggest a significant increase in ‘CC’ genotype in vitiligo patients as compared to controls, hence XBP1 rs2269577 polymorphism leads to alteration in the motif ‘AGGT’ into ‘ACGT’ in the XBP1 gene promoter." (PMID 35046957, 2021). "In conclusion, we found a common regulatory variant, rs2269577, in the promoter region of XBP1 that is associated with increased risk for vitiligo by carrying out a series of association analysis in three independent samples of the Chinese Han population." (PMID 19543371, 2009). "Through a series of genetic association and functional analyses, we have provided strong evidence for XBP1 to be a susceptibility gene for vitiligo." (PMID 19543371, 2009). "To search for susceptibility gene(s) within a genomic region showing a strong linkage to vitiligo, we interrogated a biologically plausible candidate gene, XBP1, within the region through a series of genetic association and molecular analyses." (PMID 19543371, 2009). "Interestingly, XBP1 rs2269577 was revealed to be associated with vitiligo susceptibility in Chinese and Caucasian people." (PMID 35046957, 2021). "The analysis of XBP1 rs2269577 polymorphism revealed a significant difference in allele as well as genotype frequencies among controls and patients suggesting its association with vitiligo." (PMID 35046957, 2021). "Hence, in this study, we aimed to investigate the involvement of XBP1 and IL-17A in vitiligo susceptibility in Gujarat population." (PMID 35046957, 2021). "The importance of the UPR in the pathogenesis of vitiligo is further corroborated by several lines of experimental evidence, which identified the X-box binding protein 1 (XBP1) gene, encoding a transcription factor mediating UPR activation, as a susceptibility locus for generalized vitiligo." (PMID 29163360, 2017). "Therefore, we have demonstrated that the transcriptional modulation of XBP1 expression by germ-line regulatory polymorphisms can influence the development of vitiligo." (PMID 19543371, 2009). "Given the possible functional interaction between XBP1 and HLA-DR, we investigated whether the genetic effect at rs2269577 is modified by the HLA-DR risk allele for vitiligo." (PMID 19543371, 2009). "Therefore, our study has demonstrated that the transcriptional modulation of XBP1 expression by a germ-line regulatory polymorphism has an impact on the development of vitiligo." (PMID 19543371, 2009). "Therefore, both the in-vitro and in-vivo transcriptional analyses provided consistent results, indicating that the risk-associated C allele is associated with a higher expression of XBP1 (than the wild-type G allele) which in turn is associated with the lesion development in vitiligo patients." (PMID 19543371, 2009). "In patients with vitiligo, activation of IRE1α-XBP1 signalling increases CD8+ T-cell recruitment by upregulating CXCL16 expression, thereby leading to melanocyte-specific autoimmune responses and depigmentation of the skin." (PMID 38297380, 2024).
vitiligo (continued). "Polymorphisms in UPR-linked genes, such as XBP1 and UVRAG, are associated with an increased risk of vitiligo." (PMID 35884944, 2022). "Genome-wide association studies (GWAS) have identified more than 50 genetic risk variants for vitiligo, including genes related to cytolysis (GZMB, CTLA4, FOXP3) and melanocyte function (TYR, MC1R, XBP1)." (PMID 36182982, 2022). "Distributions of genotype and allele frequencies of XBP1 rs2269577, IL17A rs2275913 and IL17A rs8193036 polymorphisms in different subsets of vitiligo patients and controls." (PMID 35046957, 2021). "Distribution of genotype and allele frequencies of XBP1 rs2269577, IL17A rs2275913 and IL17A rs8193036 polymorphisms in vitiligo patients and controls." (PMID 35046957, 2021). "Recently, a number of genes which play a role in vitiligo susceptibility, including HLA, PTPN22, NALP1, XBP1, FOXP1, IL2RA have been tested for genetic association with vitiligo." (PMID 23284977, 2012). "We further demonstrated that the association is probably due to the transcriptional modulation of XBP1 expression which was shown to be important for the development of vitiligo lesion." (PMID 19543371, 2009). "Our findings have provided the first evidence for XBP1 to play an important role in the development of vitiligo." (PMID 19543371, 2009). "Our findings have therefore not only provided insight into the genetic basis of vitiligo but also advanced our understanding on XBP1's function." (PMID 19543371, 2009). "Furthermore, XBP1, a regulator of HLA class II expression and stress responses, connects endoplasmic reticulum stress to autoimmune pathways in vitiligo." (PMID 39860439, 2025). "Activation of XBP-1 was involved in 4-TBP-induced IL-6 expression that might contribute to the autoimmune-mediated progression of vitiligo." (PMID 37627575, 2023). "XBP1 is a transcription factor that may influence the development of vitiligo through its interaction with HLA-DR molecules." (PMID 36902341, 2023). "XBP1 rs2269577 G/C, IL17A rs2275913 G/A and IL17A rs8193036 C/T polymorphisms were genotyped by Polymerase Chain Reaction-Restriction Fragment Length Polymorphism (PCR-RFLP) method in 312 controls and 276 vitiligo patients." (PMID 35046957, 2021). "Exploring the interaction of the EDNR family with cMYB and XBP1 may help to better understand the pathogenesis of vitiligo and identify treatments." (PMID 34034661, 2021). "In humans, DDR1, XBP1, NLRP1 and PTPN22 genes have been linked to vitiligo and these genes could be a starting point to investigate if animals with vitiligo are linked to the genes and mutations reported in humans." (PMID 31324191, 2019). "Given XBP1's known function as a transcription factor controlling the expression of HLA-DR, we posit that XBP1 may influence the development of vitiligo, at least partially, through its interaction with HLA-DR molecules." (PMID 19543371, 2009). "In the skin and serum of patients with vitiligo, UPR promotes the production of the chemokines IL-6 and IL-8 through the transcription factor X-box-binding protein 1 (XBP1)." (PMID 35884944, 2022). "Overall, these findings suggest XBP1 and IL17A play an important role in vitiligo and further substantiate the involvement of ER stress in exacerbating immune-mediated vitiligo pathogenesis." (PMID 35046957, 2021). "In addition, we report an increased XBP1 splicing and IL17A expression in vitiligo patients." (PMID 35046957, 2021).
lung carcinoma (17 papers, 2007 to 2025). "Here the authors show that IRE1α-XBP1 activation is associated with poor overall survival in patients with non-small cell lung cancer and that IRE1α loss in cancer cells promotes anti-tumor immune responses in lung cancer preclinical models." (PMID 36624093, 2023). "PRKCSH depletion also inhibited ER stress-induced IRE1α activation and XBP-1 splicing in lung cancer cells." (PMID 38200153, 2024). "These evidences indicated that PIE can activate XBP1 and enhance PD-L1 expression in TAMs of female offspring lung cancer mice." (PMID 38554175, 2024). "Given the selective activation of IRE1α-XBP1 lung cancer cells, we used CRISPR-Cas9 to determine the impact of IRE1α loss on HKP1 tumor progression." (PMID 36624093, 2023). "ERO1L and XBP1 can activate IL-6 pathway and promote the progression of lung cancer and HCC, respectively." (PMID 35805045, 2022). "And further experiment indicated XBP1 siRNA significantly inhibits lung cancer migration, invasion and metastasis in A549si-XBP1 and PC-9si-XBP1 compare with A549si-NC and PC-9si-NC." (PMID 34094948, 2021). "We further explored the expression of XBP1 protein in lung cancer cell lines and found that A549, H1299 and calu-1 exhibited low expression of XBP1 and PC-9 exhibited the highest expression." (PMID 34094948, 2021). "The wound-healing assay and the transwell invasion assay and metastasis assay showed that the overexpression of XBP1 promoted lung cancer cell migration, invasion and metastasis." (PMID 34094948, 2021). "Unfolded protein response (UPR) activation through the XBP1 pathway was required for high mannose expression in the human lung carcinoma cell line A549 in response to influenza and, in other work, was shown to induce high mannose in other cell lines in a cell-type specific manner." (PMID 39557836, 2024). "Accordingly, we hypothesized the mechanism by which PIE accelerates lung cancer tumorigenesis in offspring mice, possible links to IRE1α/XBP1-mediated M2-like TAMs polarization and PD-L1 up-expression." (PMID 38554175, 2024). "We further applied the online tool Lung Cancer Explorer to determine whether the high expression of XBP1 is beneficial to the survival of LUAD patients." (PMID 36092910, 2022). "Previous study demonstrated that XBP1s mRNA levels are highly expressed in lung cancer, however, the biological role and molecular mechanisms of XBP1 in NSCLC remain unknown." (PMID 34094948, 2021). "We demonstrate for the first time that XBP1 splicing is a valuable marker of lung cancer aggressiveness, and our results support a model in which IRE1 downstream signaling could act as a regulator of Epithelial to Mesenchymal Transition (EMT)." (PMID 32576923, 2020). "Given the suppression of ATG7 by NASTRp, we further examined expression of ER stress markers, such as GRP78, CHOP, IRE1, PERK, ATF6 and XBP1, to determine whether NASTRp induces ER stress in lung cancer cells." (PMID 25897662, 2015). "We found that the regions of differential methylation significantly overlapped with binding sites of Xbp1 and Etv5, transcription factors known to play a role in lung cancer tumorigenesis, suggesting that these methylation changes could interfere with transcription factor binding." (PMID 40429836, 2025). "IRE1α/XBP1-mediated M2-like TAMs polarization releases the pro-tumorigenic cytokines and PD-L1 expression, which may be the regulatory mechanism of accelerating lung cancer in offspring of mice undergoing PIE." (PMID 38554175, 2024). "IRE1α/XBP1, as the main branch of UPR signaling, can connect ER-stress and metabolic reprogramming, thereby facilitating lung cancer progression." (PMID 38554175, 2024). "Because we have found that the overexpression of XBP1 correlates with NSCLC progression and metastasis in vitro, the further experiments were used to explore the role of XBP1 in lung cancer cells’ proliferation and metastasis in vivo." (PMID 34094948, 2021).
lung carcinoma (continued). "In conclusion, these findings demonstrated that NUPR1 knockdown inhibits angiogenesis in A549 and H1299 cells through IRE1/XBP1 and PERK/eIF2α/ATF4 signaling pathways, indicating that NUPR1 could represent a novel lung cancer therapeutic target." (PMID 37854285, 2023). "Additionally, we also found that PIE induced macrophage M2 polarization in lung cancer pups of PIE group, which may be related to IRE1α/XBP1-mediated by ER stress." (PMID 38554175, 2024). "A study found that knocking down TXNDC5 along with SRXN1 reduced the time needed for splicing XBP1 and spliced XBP1, resulting in the decreased expression of HSPA5, and among the handful of proteins that interact with SRXN1, PRDX6, PDIA6, and TXNDC5 were identified in lung cancer." (PMID 38666927, 2024). "Also, transduction of lung cancer cells with Ad-IL-24 increased expression of ER stress-related proteins such as BiP/Grp78, GADD34, XBP-1 and transfection of cancer cells with ER-targeted IL-24 plasmids elicited increased apoptosis compared to proteins targeted to the nucleus or membrane." (PMID 18074024, 2007).
heart failure (16 papers, 2011 to 2024). Inability of the heart to pump blood at an adequate rate to meet tissue metabolic requirements. "Despite its role in the mechanisms underlying various cardiovascular diseases, including cardiac hypertrophy and heart failure, few studies have addressed the involvement of xbp1 in the MI context." (PMID 37958681, 2023). "Metoprolol and propranolol as b-AR blockers suppress ER stress in cardiac hypertrophy and heart failure by blocking the GRP78/CHOP/XBP-1 pathway." (PMID 36703744, 2022). "In human iPSC-derived cardiomyocytes, PAK2 (p21-activated kinase 2) activation can enhance ER function, reduce cell apoptosis, and protect from heart failure through the IRE1α/XBP1 (X-box binding protein 1)-dependent pathway." (PMID 33179756, 2020). "Certainly, future research using AAV‐mediated restoration of XBP1 in maladaptive cardiac hypertrophy is required to provide further evidence of the biological role of XBP1 in the development of heart failure." (PMID 27133203, 2016). "Because XBP1 was markedly induced in hypertrophic and failing heart, we investigated the significance of XBP1 induction and its pathophysiological role in the development of heart failure." (PMID 27133203, 2016). "And the results showed that ER stress marker GRP78 and XBP1 were significantly increased in all failing human hearts compared to normal hearts, as well as ANP, a marker associated with cardiac hypertrophy and heart failure." (PMID 27133203, 2016). "Despite these findings implicating a potential cardioprotective potential for XBP1, little is known concerning its mechanism of actions in the development of heart failure." (PMID 26572862, 2015). "Recent researches have shown the existence of spliced XBP1 (X-box-binding protein-1) and markedly increased GRP78 expression, suggesting that UPR activation is associated with the pathophysiology of heart failure." (PMID 24864159, 2014). "In patients with heart failure, the elevation of spliced XBP1 mRNA and increased BiP expression are observed, suggesting that UPR activation is associated with the pathophysiology of heart failure." (PMID 24705207, 2013). "The expression of XBP1s was decreased in the heart tissue of both human and rodents with heart failure, heart-specific XBP1 overexpression prevented the development of cardiac dysfunction, and XBP1s stimulated adaptive heart growth by activating mammalian target of rapamycin (mTOR) signal." (PMID 35321102, 2022). "In summary, our study has for the first time established that XBP1 is an important pro‐angiogenic factor, required to maintain normal cardiac function in the early stage of hypertrophy which results in the transition of hypertrophic hearts to heart failure." (PMID 27133203, 2016). "But so far, the expression trend and pathophysiological functions of XBP1 in cardiac hypertrophy and heart failure are still unknown." (PMID 27133203, 2016). "Taken together, our results suggest that XBP1 may play an important role in cardiac hypertrophy and heart failure." (PMID 27133203, 2016). "Therefore, the nature of XBP1 in other models of cardiac hypertrophy and heart failure needs to be further investigated." (PMID 26572862, 2015). "XBP1 was declined in response to miR-30* upregulation in maladaptive hypertrophy, further suggesting that miR-30* is able to directly target the XBP1 pathway, either during the period of compensated hypertrophy or during the transition to heart failure." (PMID 26572862, 2015). "Hence, the upstream regulation of XBP1 activation in heart failure should be further elucidated." (PMID 26572862, 2015). "In our study, we found that PE elevated Pak2 expression in the peri‐infarct cortex post‐stroke, consistent with a study reporting that Pak2 enhances the IRE1/XBP1 branch of the UPR and thereby prevented heart failure." (PMID 39328024, 2024).
heart failure (continued). "In a rat model of heart failure, QLQX reduced the collagen content in myocardial tissue by regulating the miR133a-endoplasmic reticulum stress-inositol-requiring enzyme 1/X-box binding protein 1 (miR133a-IRE1/XBP1) pathway." (PMID 39882321, 2024). "SERCA3f is also upregulated in heart failure, and overexpression of the Ca2+ pump, increases the XBP1 splicing and Grp78 expression; This demonstrated that SERCA3f is probably a UPR effector and participates in the ER stress in human heart failure." (PMID 36703744, 2022). "Thus, modulation of XBP1 might be a valid therapeutic target to prevent or delay heart failure." (PMID 27133203, 2016). "ER stress responses were seen in the process of cardiac hypertrophy and heart failure, as assessed by increased expression of GRP78 and spliced XBP-1." (PMID 22073308, 2011). "Accumulation of misfolded proteins in the ER (ER stress) causes the development and progression of various diseases, and fully activated XBP1, a transcription factor downstream of IRE1 in the unfolded protein response, cures persistent ER stress–induced heart failure in medaka." (PMID 37160311, 2023). "Importantly, constitutive activation of IRE1α signaling—but not ATF6α signaling—rescued this heart failure and allowed AXER-KO medaka to survive 3 d longer, likely because of XBP1-mediated transcriptional induction of ER-associated degradation components." (PMID 37160311, 2023). "Nevertheless, whether or not UPR such as XBP1 contributes to cardiac angiogenesis in hypertrophic hearts and heart failure remains to be determined." (PMID 27133203, 2016). "Persistent ER stress–induced heart failure in AXER-KO medaka was well rescued by the constitutive expression of XBP1(S) but not of ATF6α(N), allowing AXER-KO XBP1 SC/+ medaka to live 3 d longer after hatching." (PMID 37160311, 2023).